S100A4 (S100 calcium binding protein A4)
Diseases named in the same sentence as S100A4 in open-access papers (continued):
Sharing a sentence is not in itself a finding about the gene and the disease.
prostate carcinoma (continued). "Notably, S100A4 can promote invasive ability of prostate cancer cells through MMP9 and TIMP1 regulation." (PMID 23383075, 2013). "Moreover, there is evidence that S100A4 controls the invasive potential of human prostate cancer cells through the regulation of MMP9 expression, thus contributing to the invadopodia-mediated proteolytic degradation of ECM components." (PMID 24379889, 2013). "Silencing S100A4 gene expression in endothelial cells by S100A4 small-interfering RNA induces an anti-angiogenic gene signature, and administering S100A4 siRNA into human prostate cancer xenografts significantly decreased tumor vascularity and inhibited tumor growth." (PMID 36873885, 2023). "However, whether S100A4 up-regulation can alter the in vivo bone phenotype by bone metastasis of prostate cancer cells should be demonstrated in further studies." (PMID 33549040, 2021). "Therefore, targeting S100A4/embigin is a promising therapeutic strategy for prostate cancer." (PMID 30041429, 2018). "The cell response to S100A4 is receptor-mediated, cell-specific, and dependent on the conformation of S100A4 or on the association with several other receptors such as the receptor of advanced glycation end products (RAGE) on various cell types including human chondrocytes and prostate cancer cells." (PMID 29069865, 2017). "DEU patterns were much more noticeable as compared to breast and prostate cancer, with SPP1 as well as its interacting partners S100A4 and CXCL12 showing significant differences in exon usage in tumor-affected samples." (PMID 39857756, 2025). "In this regard, the S100A4 inhibitor niclosamide is currently in phase II clinical trial for metastatic colorectal cancer (NCT02519582) and prostate cancer (NCT02807805) and has completed phase I trial for prostate cancer (NCT02532114)." (PMID 33918416, 2021). "Our results demonstrated for the first time that the S100A4-embigin/AMPK/mTORC1/p21WAF1 and NF-κB/MMP9 axis is a vital oncogenic molecular cascade for prostate cancer progression." (PMID 30041429, 2018). "Notably, S100A4 secretion by fibroblasts has been shown to be stimulated by co-culture with tumor cells in vitro, and IL-1β-expressing cancer cells showed a dramatic increase of S100A4 in the stroma adjacent to skeletal metastases, that promoting early colonization of prostate cancer in vivo." (PMID 30041429, 2018). "Our results showed that embigin induces prostate cancer cells migration and activation of NF-κB, and MMP9 activation and that the migration was enhanced by extracellular S100A4." (PMID 30041429, 2018). "We propose that the S100A4-embigin/AMPK/mTORC1/p21WAF1 and NF-κB/MMP9 axis is a vital oncogenic molecular machinery exploited by a certain fraction of prostate cancers for progression." (PMID 30041429, 2018). "In the Prostate Cancer dataset, we identified some important genes with significant biological relevance, such as TMSB15A, PEDF, hepsin, KIAA0977, and S100A4." (PMID 19874631, 2009). "In the prostate cancer dataset GSE179990, PC-3 cells overexpressing NF-YA (both its short and long isoforms) showed one exon (E006) to be changed across transcripts of S100A4, or ‘ENSG00000196514’." (PMID 39857756, 2025). "In a study, S100A4 activated NF-κB through the RAGE receptor and the co-localization of S100A4 and RAGE could be detected in mice prostate cancer, indicating the significance of the S100A4/RAGE/NF-κB molecular circuitry in prostate cancer metastasis." (PMID 29069865, 2017). "Moreover, the role of S100A4 in cross-talk between prostate cancer cells and bone cells has not been investigated to date." (PMID 33549040, 2021).
osteosarcoma (30 papers, 2002 to 2023). A usually aggressive malignant bone-forming mesenchymal neoplasm, predominantly affecting adolescents and young adults. "The depletion of S100A4 expression results in the reduction of osteosarcoma cell motility and the loss of osteosarcoma cell metastatic potential, which is completely rescued by MMP-9 overexpression." (PMID 29069865, 2017). "Previously, we reported an association between S100A4 expression, matrix metalloproteinase activity and the metastatic capacity of human osteosarcoma cells." (PMID 12799648, 2003). "Several studies have demonstrated that S100A4 protein is associated with the metastasis of cancers, including osteosarcoma, that it increases the tumor metastatic capacity of cancers, and that S100A4 protein can even be a potential marker for predicting cancer metastasis." (PMID 36714568, 2022). "In addition, we have previously demonstrated an association between S100A4, matrix metalloproteinases and the invasive capacity of osteosarcoma cells." (PMID 15318945, 2004). "S100A4 is associated with the cytoskeleton and involved in the promotion of tumor invasion and metastasis not only by stimulating tumor cell motility but also via the dysregulation of MMPs and the expression of their endogenous inhibitors (TIMPs) in osteosarcoma." (PMID 29069865, 2017). "And the effect of the S100A4 protein on tumor metastasis in osteosarcoma is also accomplished through a transition in regulating OPN levels." (PMID 36714568, 2022). "Here we reduced the error of transcriptmeasurement, exemplarily demonstrated for the target gene S100A4 and dog osteosarcoma, a comparative oncology model." (PMID 32296879, 2020). "For example, miR-187-3p inhibits the metastasis and EMT in hepatocellular carcinoma and osteosarcoma by targeting S100A4." (PMID 32842846, 2020). "As a first demonstration of technical noise reduction in transcriptquantification achieved by our improved normalization strategy, we evaluated theextent of pairwise co-expressions among the S100A4 transcripts a, b and c acrosscanine osteosarcomas." (PMID 32296879, 2020). "Relaxin-2 (RLN2) increases osteosarcoma cell migration, invasiveness, proliferation, and participates in the activation of the S100A4/MMP-9 signaling." (PMID 29069865, 2017). "S100A4-mediated osteosarcoma metastasis occurs upon the activation of pro-MMP-2 and higher cell-density for the expression of SN50, a peptide inhibitor of NF-κB nuclear translocation." (PMID 29069865, 2017). "Early attempts to reduce the mRNA and protein level of S100A4 in the late 1990s reported successful reduction of the S100A4-induced metastatic phenotype for osteosarcoma, in vitro as well as in vivo." (PMID 27331819, 2016). "Other authors using an osteosarcoma cell line or chondrocytes observed a correlation between S100A4 and MMP activation." (PMID 24023743, 2013). "Our group has previously shown that extracellular S100A4 induces the expression of ephrin-A1 and osteopontin in osteosarcoma cell lines by activating the transcription factor NF-κB." (PMID 22853000, 2012). "The metastasis-promoting protein S100A4 induces expression of ephrin-A1 and osteopontin in osteosarcoma cell lines." (PMID 22853000, 2012). "Our group has previously shown that extracellular S100A4 induces the expression of ephrin-A1 and osteopontin in osteosarcoma cell lines." (PMID 22853000, 2012). "In the present study we used a human osteosarcoma cell line to demonstrate that extracellular S100A4 activates the IKK complex and induces NF-κB activity independent of the postulated S100 receptor RAGE." (PMID 20507646, 2010).
osteosarcoma (continued). "The addition of extracellular S100A4 has been shown to induce NFκB activity in a low S100A4 expressing osteosarcoma cell line, but the possibility of a PTM being involved in such activation has yet to be explored." (PMID 18554396, 2008). "In the present work, we found that the S100A4-expressing human osteosarcoma cell line OHS was more sensitive to IFN-γ-mediated apoptosis than the II-11b cells." (PMID 15318945, 2004). "We have previously observed that the human osteosarcoma cell line OHS is more sensitive to IFN-γ induced apoptosis than the S100A4-ribozyme transfected counterpart II-11b." (PMID 15318945, 2004). "S100A4 secretion by human osteosarcoma cells is in agreement with previous reports showing that S100A4 can be released from non-malignant as well as tumor cells." (PMID 15318945, 2004). "Searching for cytokines and signal transduction modulators affecting S100A4 expression, we recently discovered that IFN-γ downregulated S100A4 transcription and induced apoptosis in the human osteosarcoma cell line OHS." (PMID 15318945, 2004). "In the present study, we have demonstrated that the Ca2+-binding protein S100A4 sensitizes human osteosarcoma cells to IFN-γ-induced apoptosis." (PMID 15318945, 2004). "In conclusion, we have shown that S100A4 sensitizes osteosarcoma cells to IFN-γ-mediated induction of apoptosis." (PMID 15318945, 2004). "In the present study, we show that S100A4 can be secreted from these human osteosarcoma cells, and that extracellular addition of rS100A4 sensitizes cells to apoptosis induced by IFN-γ." (PMID 15318945, 2004). "The S100A4 response was observed at an earlier time point and at a lower dose in the osteosarcoma compared to the carcinoma cell lines." (PMID 12799648, 2003). "We have previously shown, using a specific ribozyme transfected into highly metastatic S100A4 expressing human osteosarcoma cells, that reduced expression of S100A4 leads to a nearly complete reversal of the metastatic phenotype in an animal model." (PMID 12439718, 2002). "Recent studies show that the inhibitor of TGF-β signals which are associated with metastasis and chemoresistance of osteosarcoma, LY2109761, could inhibit metastasis and enhances chemosensitivity of osteosarcoma by the downregulation of S100A4 expression." (PMID 29069865, 2017). "Interestingly, in osteosarcoma cell lines, S100A4-mediated NFκB activation occurred independently of RAGE, indicating further receptors or receptor complexes interacting with S100A4." (PMID 24952599, 2014). "Importantly, H-7 and staurosporine displayed a potent and dose dependent inhibition of S100A4-induced NF-κB activation in a luciferase based activity assay, both using II-11b cells and the human osteosarcoma cell line KPDX." (PMID 20507646, 2010). "In addition, when examining S100A4 from the osteosarcoma cell line OHS, the same pattern was observed." (PMID 18554396, 2008). "A recent study demonstrated that S100A4 induces NF-κB-dependent expressions and secretions of SPP1 in osteosarcoma cell lines." (PMID 35721061, 2022). "Cell cultures from two human osteosarcoma cell lines, OHS and its anti-S100A4 ribozyme transfected counterpart II-11b, was treated with IFN-γ and recombinant S100A4 in order to study the sensitizing effects of extracellular S100A4 on IFN-γ mediated apoptosis." (PMID 15318945, 2004). "An earlier study using MVs from human osteosarcoma Saos-2 cells showed the presence of S100A4 and S100A6 but not S100A11." (PMID 36979349, 2023). "So, how exactly do S100A4 protein and OPN link and affect osteosarcoma metastasis?" (PMID 36714568, 2022). "The human osteosarcoma cell line II-11b was stimulated with recombinant S100A4 in the presence or absence of inhibitors of common signal transduction pathways, and NF-κB activity was examined using a luciferase-based reporter assay and phosphorylation of IκBα." (PMID 20507646, 2010).
osteosarcoma (continued). "TIMP2 is involved in matrix degradation and invasion, and is down-regulated in Motif 1 cell lines in this study, which is consistent with its role in inhibiting matrix metalloproteinases, and agrees with the inverse correlation shown between S100A4 and TIMP2 in osteosarcoma cells." (PMID 20041153, 2009). "Notably, both WiDr and PM1 cells responded with induction of STAT1 after incubation with 50 U ml−1 IFN-γ for 48 h (results not shown), suggesting that the difference in S100A4 response could not be explained by increased sensitivity to IFN-γ in the osteosarcoma cells in general." (PMID 12799648, 2003).
glioblastoma (26 papers, 2015 to 2026). The most malignant astrocytic tumor (WHO grade IV). "Furthermore, gene expression of four tested GSC markers (CD133, SOX11, ALDH1A3, S100A4) was markedly reduced upon REST loss compared with wild-type glioblastoma cells." (PMID 38609948, 2024). "In the present study, we show that the transcription factor C/EBPβ directly regulates the expression of metastatic protein S100A4 in a mouse glioblastoma cell line and that this regulation may underlie the effects of C/EBPβ in the invasiveness of glioblastoma cells." (PMID 25738360, 2015). "In glioblastoma, S100A4 is a novel marker, regulator, and critical upstream regulator of the mesenchymal transition." (PMID 36499426, 2022). "It has been reported that S100A4 is a novel biomarker of glioblastoma stem cells, the increased expression of which contributes to the emergence of a metastatic phenotype." (PMID 36235175, 2022). "S100A4 was recognized as a prognostic marker, metastasis promoter, and regulator in several cancers, including glioblastoma, head and neck cancers, and colorectal cancer." (PMID 32429463, 2020). "Our data also point to a role of S100A4 in glioblastoma cell invasion and suggest that the C/EBPβ gene controls the invasive potential of GL261 and T98G cells through direct regulation of S100A4." (PMID 25738360, 2015). "Here, we have evaluated the possible role of S100A4 in the observed effects of C/EBPβ in glioblastoma cells and the mechanism through which S100A4 levels are controlled by C/EBPβ." (PMID 25738360, 2015). "Next, we determined the effect of C/EBPβ depletion and S100A4 overexpression on invasion and motility in the human glioblastoma cell line T98G." (PMID 25738360, 2015). "The expression of S100A4 is very low in both mouse GL261 and human T98G glioblastoma cells depleted of C/EBPβ, which is associated with a decreased in migration and invasiveness capacity of these cells." (PMID 25738360, 2015). "This reduction in C/EBPβ levels was accompanied by a large reduction in S100A4 levels, indicating that C/EBPβ is also able to regulate S100A4 expression in the subpopulation of glioblastoma stem cells." (PMID 25738360, 2015). "SFN-Cys may disrupt microtubules, modulate mitophagy, and alter the expression of S100A4 and Claudin-5 to inhibit migration and invasion in glioblastoma (GBM) cells." (PMID 40597933, 2025). "Additionally, this study discovered that S100A4 acts as an upstream regulator of the master EMT in glioblastomas, due to it can regulate SNAIL2, ZEB and other mesenchymal transition regulators." (PMID 36046652, 2022). "S100A4 was found to function upstream of master EMT regulators such as Snail2 in glioblastoma." (PMID 33549040, 2021). "Furthermore, overexpression of S100A4 in C/EBPβ-depleted glioblastoma cells reverses the enhanced migration and motility induced by this transcription factor." (PMID 25738360, 2015). "Overall, our findings suggest that targeting C/EBPβ in glioblastoma cells could have a therapeutic benefit by directly inhibiting the S100A4 gene, which is known to be involved in tumor invasiveness." (PMID 25738360, 2015). "All these data together prompted us to analyze whether C/EBPβ is a direct regulator of S100A4 expression and if this protein could mediate the observed effects of C/EBPβ on migration and invasiveness of glioblastoma cells." (PMID 25738360, 2015). "Collectively, these studies show that C/EBPβ increases S100A4 levels by directly activating S100A4 promoter expression in glioblastoma cells and provide evidence that S100A4 may contribute to the C/EBPβ-induced invasiveness." (PMID 25738360, 2015). "Thus, targeting C/EBPβ in glioblastoma cells is therapeutically strategic to block the S100A4 gene." (PMID 32429463, 2020). "Also, we demonstrate that S100A4 promotes migration and invasiveness of glioblastoma cells." (PMID 25738360, 2015). "S100A4 depletion lengthened the anti-VEGF treatment profile and hence reduced glioblastoma resistance to antiangiogenic therapy." (PMID 32429463, 2020).
glioblastoma (continued). "Recently, the putative markers frequently being used to identify and/or isolate glioblastoma stem cells (GSCs) include: CD133, CD44, CD15, CD70 (CD27 L), S100A4, ALDH1A3, Nanog, OCT-4, SOX-2, and Nestin." (PMID 32429463, 2020). "Our results show that C/EBPβ suppression significantly reduced the levels of S100A4 in murine GL261 and human T98G glioblastoma cells." (PMID 25738360, 2015). "S100A4 is an upstream regulator of epithelial-mesenchymal transition (EMT) master regulators SNAIL2 and ZEB, as well as other mesenchymal transition regulators of glioblastoma." (PMID 34148033, 2021). "S100A4 is a well-known inductor of tumor cell motility and metastasis in different cancer cells, although its role in the invasiveness capacity of glioblastoma cells is not yet known." (PMID 25738360, 2015). "Here, we have also analyzed whether S100A4 was also present in the GCSC subpopulation and if its expression was also regulated by C/EBPβ, as it happened in adherent glioblastoma cells." (PMID 25738360, 2015). "S100A4 regulates immunosuppressive T cells and myeloid cells in glioblastoma, the deletion of S100A4 in non-tumor cells is sufficient to reprogram the immune landscape and significantly enhance survival rates, indicating its potential as a target for immunotherapy." (PMID 40093000, 2025). "In addition, HIF1α is involved in the regulation of miR-210-3p, CXCR7, CXCR4, IDH1, C-Met, SF/HGF, the S100A4/NMIIA axis, NO, VEGF, BAG3, and TDO2, and influences various aspects of the glioblastoma biology such as angiogenesis, invasion, metabolism, and therapy resistance." (PMID 38893207, 2024).